CXCR4 (C-X-C motif chemokine receptor 4)
Diseases named in the same sentence as CXCR4 in open-access papers (continued):
Sharing a sentence is not in itself a finding about the gene and the disease.
tumor (continued). "Immunohistochemical expression of CXCR4 was observed predominantly in the cytoplasm of tumor cells." (PMID 20953377, 2010). "Correlation of CXCR4 expression in tumour cells with clinicopathological patient characteristics." (PMID 20386750, 2010). "In addition, inhibition of CXCR4 function by the administration of AMD3100, CXCR4-specific peptide antagonist, can dramatically impair tumor formation and metastasis." (PMID 20380740, 2010). "Differences in CXCR4 expression in adjacent liver tissue and tumor tissue of HCC with PVTT." (PMID 21110890, 2010). "NSCLC tumor and metastases were also assessed for the presence of CXCR4." (PMID 19563666, 2009). "We also found that the level of CXCR4 expression correlated with bone metastasis-free survival; i.e., HCC patients with tumor tissue exhibiting strong CXCR4 expression may experience bone metastases sooner than those with lower levels of expression." (PMID 19508713, 2009). "We hypothesize that CXCR4 participates in HCC cell homing to bone or bone marrow and that primary tumor CXCR4 expression correlates with clinical metastasis to bone." (PMID 19508713, 2009). "The expression of CXCR4 on tumor cells may represent a critical biomarker for their propensity to metastasize." (PMID 19563666, 2009). "Moreover, the addition of 4F-benzoyl-TE14011, a CXCR4 antagonist, to the environment reduces tumor cell invasion." (PMID 19719844, 2009). "Finally, potential signals activated downstream SDF-1α/CXCR4 and involved in lung homing of E6/E7-expressing tumor cells were investigated." (PMID 19325708, 2009). "Indeed, SCLC cell lines and primary tumour cells express high levels of CXCR4, and CXCR4 ligand CXCL12 is constitutively expressed by bone marrow stromal cells." (PMID 19455144, 2009). "This concept supports the notion that expression of CXCR4 on tumor cells may represent a critical biomarker for their propensity to metastasize." (PMID 19563666, 2009). "CXCR4 may play an important role in the metastasis of HCC by promoting the migration of tumor cells." (PMID 19508713, 2009). "CXCR4 is a chemokine receptor frequently overexpressed on primary tumor cells." (PMID 19325924, 2009). "High expression of CXCR4 has however been described in NCI-N592 underlying the heterogeneity of SCLC cell lines and reflecting heterogeneity among SCLC diagnosed tumours themselves." (PMID 19455144, 2009). "Moreover, we recently revealed that the expression of CXCR4 in OSCC at the primary site was significantly associated with lymph node metastasis, mode of invasion, tumor recurrence, and patient prognosis." (PMID 19671192, 2009). "This study was performed to evaluate the hypothesis that CXCR4 may be a marker for circulating tumor cells in metastatic NSCLC." (PMID 19563666, 2009). "Normal tissue adjacent to tumor cells occasionally showed weak CXCR4 staining in the cytoplasm." (PMID 19508713, 2009). "Patients with high CXCR4 tumour expression clearly had a worse outcome than those with low CXCR4 expression (OS: 9.7 months (95% CI: 6.0–13.4) vs 43.2 months (95% CI: 16.3–78.1), P=0.0006; DFS: 8.6 months (95% CI: 5.8–11.3) vs 12.4 months (95% CI: 10.7–14.0, P=0.067)." (PMID 19352387, 2009). "CXC chemokine receptor 4 (CXCR4) also promotes tumor metastasis." (PMID 19580679, 2009). "Such metastatic foci mainly comprised >90% CXCR4+ tumor cells (‘Untreated Control’)." (PMID 19325708, 2009). "Since CXCL12 is expressed preferentially in lymph nodes, this may support our finding that CXCR4 expression was significantly correlated with lymph node metastasis in human PTC tumor samples." (PMID 18826577, 2008). "Recent evidence suggests that tumor production of CXCR4 promotes lymph node metastasis." (PMID 18826577, 2008). "Furthermore, The previous views suggested that tumor cells express high CXCR4 and the metastasis-targeted organs express high CXCL12, so the tumor cells were attracted to the ligand in these organs." (PMID 18983683, 2008).
tumor (continued). "Similar to the relationship between VEGF and CXCR4, CXCR4 may be involved in promoting VEGF-C-mediated tumor lymphangiogenesis or invasiveness of cancer cells." (PMID 19025611, 2008). "CXCR4 expression was significantly positive in CRCs with high tumour stage and with LN metastasis." (PMID 18443596, 2008). "Moreover, comparison of CXCR4-negative and CXCR4 nuclear-type-positive CRCs revealed that malignant potential, as indicated by tumour stage, lymphatic invasion, venous invasion, and LN metastasis, was clearly higher in CXCR4 nuclear-type-positive tumours." (PMID 18443596, 2008). "However, contrary to expectation, even CRC patients with nuclear patterns of CXCR4 expression in the primary lesion frequently had cytomembrane-type CXCR4-positive tumours in the LNs." (PMID 18443596, 2008). "Among the family of chemokines and their receptors that significantly contribute to the initiation, progression, invasion and metastasis of tumors, tumor cells expressing high CXCR4 are often found in tissue expressing CXCL12, perhaps due to organ-specific metastasis." (PMID 18983683, 2008). "In addition, at least in breast cancercells, inhibited CXCR4 ubiquitinationwas described as another mechanism contributing to increased CXCR4 surface levels." (PMID 19266088, 2008). "Furthermore, it was reported that CXCR4 surface expressionwas higher in permanent cell lines than in primary tumor samples." (PMID 19266088, 2008). "Furthermore, a recent report demonstrated that a subpopulation of CD133+ CXCR4+ cells was responsible for tumour metastasis." (PMID 18349830, 2008). "Recent studieshave shown that a unique population of CXCR4+ stem cells may be crucial forexpansion of tumor cell populations." (PMID 18779872, 2008). "At the same time, MMPs can similarly induce CXCR4 expression in tumor cells." (PMID 18983683, 2008). "In our study, tumor cells not only expressed CXCR4, but also CXCL12." (PMID 18983683, 2008). "Thus, an accurate assessment of the CXCR4 status of a given tumor specimen would provide valuable predictive information for disease prognosis and possible therapeutic intervention." (PMID 19116653, 2008). "Intensity of CXCR4 expression was correlated with both tumor and patient characteristics." (PMID 19266088, 2008). "We therefore investigated whether CXCR4 overexpression in NB tumour cells could influence organ-specific invasive behaviour in our in vivo model." (PMID 17925864, 2007). "Nevertheless, some tumour cells, possibly equipped with unidentified particularly invasive characteristics, do escape the primary tumour and may then use the CXCR4/CXCL12 axis to specifically migrate toward CXCL12 producing organs such as the liver." (PMID 17925864, 2007). "In contrast, the strong growth-promoting effect observed may represent the main role of CXCR4 in tumour progression." (PMID 17925864, 2007). "Relative risk of patients with positive CXCR4 expressing tumours but negative staining for SDF-1 was not significantly higher compared with patients with negative CXCR4 expressing tumours in the same background (relative risk of 1.57, P=0.281)." (PMID 17245339, 2007). "To evaluate the role of CXCR4 in the development of site-specific metastasis we used the orthotopic NB mouse model that strongly implies the role of the tumour microenvironment on tumour progression." (PMID 17925864, 2007). "This suggests a tumour type specific effect of CXCR4 in promoting invasion." (PMID 17925864, 2007). "CXCR4 is the chemokine receptor most commonly found on tumour cells." (PMID 17925864, 2007). "Recent reports indicate that CXCR4 is commonly expressed on NB metastasis in the bone marrow and that it may be actively contributing to NB tumour cell homing to the bone marrow." (PMID 17925864, 2007). "CXCR4 expression in the NB8 cell line dramatically accelerated tumour growth." (PMID 17925864, 2007).
tumor (continued). "There has recently been an overwhelming amount of evidence suggesting that the CXCR4/CXCL12 chemokine signaling axis may play an integral role in the metastatic progression of many tumor types." (PMID 18001467, 2007). "Furthermore, elevated CXCR4 expression was detected in several human RCC cell lines and tumor samples, while only minimal CXCR4 expression was detected in normal kidney tissues." (PMID 17083723, 2006). "Since then, CXCR4 expression has been reported in at least twenty three epithelial, mesenchymal and hematopoietic cancers, suggesting the importance of this ligand/receptor axis, in general in tumor metastasis." (PMID 17083723, 2006). "We observed different staining patterns of CXCR4 in NPC tumor cells: 135 showed nucleus staining, 18 nucleus and cytoplasm staining, 2 nucleus and cytoplasm and membrane staining, 14 cytoplasm staining, 22 cytoplasm and membrane staining, 2 membrane staining and one negative staining." (PMID 15978137, 2005). "Furthermore, recent evidence points to the SDF-1α-CXCR4 complex as having a role in progression to metastasis in several tumor contexts." (PMID 16457694, 2005). "Consequently, we hypothesized that the temporal elevation of CXCR4 expression in tumor‐infiltrated CD8+ T cells promotes their migration toward CXCL12‐expressing CAFs." (PMID 41257391, 2026). "Thus, CXCR4 blockade has been further explored as an attractive drug target to synergize with traditional immunotherapeutic agents, particularly in immunologically ‘cold’ or immune-excluded tumours." (PMID 41601679, 2026). "Moreover, cellular components such as cancer-associated fibroblasts (CAFs), tumor-associated macrophages (TAMs), and regulatory T cells (Tregs) drive immune evasion and therapeutic resistance via cytokine signaling axes, including IL-6/STAT3 and CXCL12/CXCR4." (PMID 42294061, 2026). "Therefore, it is possible that the diurnal phase of Cxcr4 expression observed in tumor‐infiltrated CD8+ T cells of LLC1‐bearing mice may be opposite to those in humans." (PMID 41257391, 2026). "In addition, endothelial cells of large vessels in the tumor stroma also overexpressed the CXCR4 receptor, suggesting that the CXCR4/CXCL12 axis may be highly involved in tumor angiogenesis." (PMID 40142155, 2025). "Finally, CXCR4 expression has been correlated with both disease stage and tumor histology." (PMID 41149503, 2025). "Furthermore, the interaction between the MIF pathway and its ligands, CD74/CXCR4, may play a important role in promoting tumor metastasis." (PMID 41127012, 2025). "The significant association between Hg levels and CXCR4 expression identified in our case series suggests that abnormal Hg accumulation in tumor tissue may contribute to pro-tumoral molecular pathways mediated by CXCR4, a key regulator of metastasis and tumor progression." (PMID 40362664, 2025). "In fact, it has been seen that patients with low CXCR4 expression in cytotoxic T lymphocytes in peripheral blood have a better efficacy to anti-PD-1 ICIs in NSCLC because probably they are receiving trafficking orders from a higher expression of CXCL12 in tumor tissue." (PMID 41149503, 2025). "Also, non-radiolabeled “cold” CXCR4 antagonists such as Plerixafor may have a role in decreasing tumor proliferation in patients demonstrating CXCR4 expression in PET/CT imaging." (PMID 40075611, 2025). "However, tumor vasculature is heterogeneous, and the exact mechanism by which CXCR4 inhibition induces tumor necrosis remains unclear." (PMID 41210695, 2025). "This ADC selectively eliminated CXCR4-overexpressing metastatic cells both in vitro and in vivo, achieving full inhibition of tumor growth in a lung-seeding cancer model, while causing a modest effect on non-target CXCR4+ hematopoietic cells at the bone marrow." (PMID 40307933, 2025).
tumor (continued). "Fourth, appropriate PET radiopharmaceuticals need to be selected for tumor imaging (FDG or Ga-68-FAPI (fibroblast activating protein inhibitor) targeting cancer associated fibroblasts) and inflammation imaging (FDG or Ga-68-Pentixafor targeting chemokine signals (CXCL12/CXCR4 pathway), respectively." (PMID 40612332, 2025). "CXCR4 has a key role in tumor cell migration and homing to metastatic sites, and exercise-induced increases in blood flow, oxygenation, and tissue perfusion may enhance the recruitment of immune cells, indirectly upregulating CXCR4 expression as part of a stress-adaptive response." (PMID 40699773, 2025). "Therapeutic approaches that preserve vascular stability or focus on the molecular mechanisms (e.g., CXCR4, E-selectin) which hold dormant cells could stop metastatic relapse by maintaining disseminated tumor cells (DTCs) in a dormant state or enhancing their responsiveness to treatment." (PMID 41465319, 2025). "Its association with CXCR4, HHLA2, and RAET1E points to a potential role in immune cell recruitment and NK/T‐cell activation, which could contribute to an altered immune landscape in the tumor microenvironment." (PMID 40952239, 2025). "In addition to structural impediments, CAFs contribute to spatial immune exclusion through the secretion of chemokines such as CXCL12, which activates the CXCR4 signaling axis and creates a chemotactic barrier that restricts immune cell localization to the tumor periphery." (PMID 41341574, 2025). "Reported in a recent preprint, [212Pb]Pb-Pentixather increased survival in murine CXCR4 tumour models, though the risk of myelotoxicity clinically was noted due to the greater affinity of Pentixather for the human CXCR4 isoform expressed on hematopoietic stem cells." (PMID 40591218, 2025). "This analysis revealed an increase in CXCR4 expression in both tumoral and metastatic lesions, highlighting the potential role of CXCR4 in cancer progression (Kruskal–Wallis test p < 0.0001; normal vs. tumor p < 0.0001; normal vs. metastatic p < 0.0001; tumor vs. metastatic p < 0.0001)." (PMID 40362664, 2025). "In this study, cells of phase G1 significantly increased, and cells of S and G2/M phases significantly decreased in cells treated with TN14003 and CXCR4-LV1, suggesting that CXCR4 downregulation could induce phase G1 arrest and apoptosis as well as inhibit tumor cell proliferation." (PMID 41445742, 2025). "Moreover, the CXCL12γ isoform has been shown to accelerate tumor progression in CRPC by promoting the PCSC phenotype via CXCR4-mediated PKCα/NF-κB activation, resulting in an increase in the population of CD133+CD44+ CSC-like cells in CXCL12γ-overexpressing tumors." (PMID 40735647, 2025). "Similarly, CXCR3 and CXCR4 play pivotal roles in regulating the migration of immune cells to the tumor microenvironment, a process that not only supports immune evasion but also aids in tumor metastasis to distant organs." (PMID 41024311, 2025). "Finally, cancer-associated fibroblasts (CAFs), identified by their high expression of CAF markers, interacted with EPCs and CD34+ Pro-B cells via CXCL12/CXCR4, promoting tumor progression and angiogenesis, as found in many tumor studies where CAFs promote tumor invasion via CXCL12/CXCR." (PMID 40990011, 2025). "However, pertaining to the co-stimulatory effects of chemokine receptors in TCR-mediated T cell activation, we also argue that outfitting BCMA CAR-expressing NK-92 cells with CXCR4 endows these cells with an enhanced ability to kill BCMA antigen-expressing tumor cells on a cellular level." (PMID 38979422, 2024). "Thus, activation of the CXCL12/CXCR4/MAPK pathway is important for tumour growth and metastasis." (PMID 38766687, 2024). "Interestingly, this MDMX-associated upregulation of CXCR4 is only observed in cells grown in the tumor microenvironment (TME), but not in MDA-MB-231 cells grown in a tissue culture dish." (PMID 39766093, 2024).
tumor (continued). "Therefore, inhibition of CXCR4/CXCL12 or Tie2 kinase may serve as a target to prevent tumor intravasation." (PMID 39003350, 2024). "Furthermore, disulfidptosis activity also showed tight correlations with tumors at scRNA‐seq, and pairs, such as MIF_CD74_CD44, MIF_CD74_CXCR4, MDK_NCL, and APP_CD74, might be potential targets in disulfidptosis‐related tumor microenvironment." (PMID 38420162, 2024). "In addition to metastasis, CXCR4/SDF1 has been demonstrated to contribute to tumor proliferation." (PMID 39619207, 2024). "This study considers the possibility that CXCR4-tropic HIV could inhibit tumor-promoting macrophages and the potential for CXCR4-tropic HIV to induce apoptosis in breast cells independently of CD4 interaction, suggesting a unique mechanism by which these HIV variants might reduce BC risk." (PMID 38542195, 2024). "Interestingly, our data showed that the extended lifespan of neutrophils could greatly contribute to the increased percentage and accumulation of aged CXCR4+ neutrophils within the tumor." (PMID 39447112, 2024). "Therefore, we hypothesized that the combination of FAP-targeted RPT and CXCR4 antagonist would effectively treat TNBC by direct tumor killing and TME reprogramming." (PMID 38587644, 2024). "Thus, CXCR4 targeting is a strategy to inhibit Tregs activity in the RCC tumour microenvironment." (PMID 38704478, 2024). "We suggest that CXCR4 expression in the post-neoadjuvant setting could identify tumors with cancer stem cells that are resistant to neoadjuvant treatment and may be involved in tumor relapse, eventually impacting survival." (PMID 38893721, 2024). "Furthermore, the CXCL12/CXCR4 has been recognized as a prognostic marker in different cancers and preclinical models; signifying that metastasis is mediated by CXCR4 activation and migration of tumor cells towards CXCL12 expressing organs." (PMID 38877052, 2024). "Similarly, AMD31100 coated on synthetic protein nanoparticles (AMD3100-SPNPs) delivered to a glioblastoma mouse model inhibited tumor proliferation and reduced infiltration of CXCR4+ MDSCs while overcoming poor pharmacokinetic properties of AMD3100 and restoring the blood-brain barrier." (PMID 39114657, 2024). "Consequently, P-BS-CM1 → P-PS-CM2 (+) primed anti-cancer immunity in the local tumor microenvironment, partially through amplified ICD-inducing PDT recruiting CD8+ T cells into the tumor bed, and partially through escalated CXCR4 clustering reducing immunosuppressive Tregs and MDSCs." (PMID 38553476, 2024). "Moreover, the inhibition of SDF-1/CXCR4 signaling can potentiate the action of other immunotherapeutic agents by improving the infiltration of effector T cells into the tumor core, a region that is typically characterized by hypoxia and high levels of immunosuppressive cytokines." (PMID 39195225, 2024). "This suggests that the orchestration of CXCR4 pre-targeting and clustering by P-BS-CM1 → P-PS-CM2, which potentiated PDT by alleviating tumor hypoxia and increasing susceptibility, exceeded the tumor accumulation benefits conferred by multivalent CXCR4 targeting in the P-BS-PS group." (PMID 38553476, 2024). "Therefore, the anti-CXCR4-NaGdF4 NDs could be employed as a targeting nanomedicine for detection and biotherapy of CXCR4-overexpression tumor." (PMID 38982161, 2024). "Notably, chemokine receptors, including C-C chemokine receptor type 2, 4, 5, 6, 8, 10 (CCR2, CCR4, CCR5, CCR6, CCR8, CCR10), and C-X-C chemokine receptor type 3, 4 (CXCR3, CXCR4) have been identified as significant factors in the recruitment of Treg cells to the tumor site." (PMID 39000453, 2024). "The question remains why, in the xenograft tumor model, the MDMX-associated upregulation of CXCR4 was a result of an increase in mRNA and protein, and why, in this exogenous model of the addition of CXCL12, the only increase observed was in the CXCR4 protein levels." (PMID 39766093, 2024).